LYVE1 (lymphatic vessel endothelial hyaluronan receptor 1)
Diseases named in the same sentence as LYVE1 in open-access papers (continued):
Sharing a sentence is not in itself a finding about the gene and the disease.
Lupus (2 papers, 2013 to 2025). "Inhibition of VEGFR-3 by oral SAR131675 treatment decreased the resiquimod-induced glomerular and tubulointerstitial inflammation and attenuated LYVE-1 (+) lymphatic vessel expression in the murine lupus model." (PMID 40651955, 2025). "Our current study shows an increase in lymphangiogenic factors such as Lyve-1, Pdpn, Prox-1, and Vegfr3 mRNA in our lupus model." (PMID 40651955, 2025).
macular holes (2 papers, 2021 to 2025). A hole in the macula of the retina. "For example, samples of the pre-macular bursa collected from macular hole patients expressed lymphatic vessel endothelial hyaluronan receptor 1 (LYVE-1)." (PMID 39940795, 2025). "BS, BPM, and VC specimens were selectively collected in macular hole and epiretinal membrane patients during vitrectomy and were then immunostained with antibodies for podoplanin, LYVE-1, and fibrillin-1 and -2." (PMID 33669860, 2021).
mammary adenocarcinoma (2 papers, 2024 to 2025). "A recent study on mammary adenocarcinoma showed that perivascular LYVE1+ TAMs secrete the platelet-derived growth factor-C (PDGF-C) homodimer, PDGF-CC, which signals to PDGF receptor-α (PDGFRA)-expressing stromal cells involved in blood vessel formation." (PMID 41203997, 2025). "In a murine model of mammary adenocarcinoma, LYVE-1+ macrophages were found to localize near blood vessels and help maintain perivascular pericyte-like cells throughout tumor development." (PMID 38717149, 2024).
oral cancer (2 papers, 2021 to 2023). "Although studies have not directly established LYVE1 as a target for either miR-141 or miR-34a, increased LYVE1 expression has been shown to be associated with increased rate of LNM in oral cancer." (PMID 34316330, 2021).
osteosarcoma (2 papers, 2022 to 2025). A usually aggressive malignant bone-forming mesenchymal neoplasm, predominantly affecting adolescents and young adults. "Osteosarcoma cells, MDSCs, and LYVE1+ macrophages were comparable between the two samples, indicating commonalities between tumors." (PMID 40647416, 2025). "In primary osteosarcoma tissues, we noticed six macrophage subsets, while an additional LYVE1+ interstitial macrophage subset was noticed in MPE samples." (PMID 36305631, 2022). "Osteosarcoma cells polarized macrophages to an M2 phenotype via CSF1 and CSF1R, and interactions between LYVE1+ and angiogenic macrophages through CCL2 and CCR1 promoted a proangiogenic niche and inflammatory responses." (PMID 40647416, 2025).
sarcopenia (2 papers, 2022 to 2024). Progressive decline in muscle mass due to aging which results in decreased functional capacity of muscles. "To investigate the immune microenvironment in different states, we calculated the percentages of immune cell types in each sample, and compared the results among the young, aged and sarcopenia groups as well as between the LYVE1-high and LYVE1-low groups." (PMID 39026669, 2024). "Our findings suggest a correlation between LYVE1+ macrophage expression and sarcopenia, as well as significant functional and metabolic differences between the high and low LYVE1 expression groups." (PMID 39026669, 2024). "Furthermore, by analyzing bulk RNA-seq data, we examined the gene expression signature, functional differences, and infiltration characteristics of the young, aged, and sarcopenia groups, as well as the LYVE1-high and LYVE1-low groups." (PMID 39026669, 2024). "During sarcopenia, LMHFV or Mg could suppress muscle inflammation (C/EBPα and LYVE1) and modulate M2 macrophages in this study." (PMID 36361730, 2022).
synovitis (2 papers, 2016 to 2022). Inflammation of a synovial membrane. "Previously we reported that TNF-Tg mice develop ankle synovitis and significantly increased numbers of LYVE-1+ lymphatic vessels." (PMID 27239212, 2016).
uveal melanoma (2 papers, 2019 to 2021). A melanoma derived from melanocytes of the uveal tract. "Podoplanin and LYVE-1 are also implicated in uveal melanoma." (PMID 33669860, 2021). "Two samples of the 16 uveal melanomas showed focal positive intraocular vascular staining for LYVE-1 and co-expression of CD31 and CD34." (PMID 30781402, 2019).
acute kidney injury (1 paper, 2024). Sudden and sustained deterioration of the kidney function characterized by decreased glomerular filtration rate, increased serum creatinine or oliguria. "Lyve1 marks lymphatic endothelial cells and plays a significant role during inflammation, which is critical in acute kidney injury (AKI) and its transition to CKD." (PMID 39064752, 2024).
adenocarcinomas of the colon (1 paper, 2006). "In addition, in adenomas and adenocarcinomas of the colon we detected LYVE-1 positive lymphatic vessels reaching the tumor through the stromal stalk and penetrating through the connective tissue (lamina propria) into the tumor, a characteristic not described so far." (PMID 17118177, 2006).
aortic aneurysm (1 paper, 2022). A ruptured aneurysm located in the wall of the proximal portion of the descending aorta proceeding from the arch of the aorta. "Tissue-resident macrophages express the lymphatic vessel endothelial hyaluronan receptor-1 (LYVE-1), but their role in aortic aneurysm formation and progression remains unknown." (PMID 36329047, 2022). "At more advanced stages, in Jak2V617F mutant mice with large aortic aneurysm, another dominant subset of macrophages expressing Ccr2, but not Lyve1, has been identified in the aortic wall." (PMID 36329047, 2022). "However, at more advanced stage, most of CD68+ macrophages in Jak2V617FHC-EC mice with severe aortic aneurysm did not colocalize with LYVE-1+ staining." (PMID 36329047, 2022).
Arthritis (1 paper, 2025). Inflammation of a joint. "Together, Lyve1+;Vegfr3+ double-positive tube-like structures are identified as lymphatic vessels, which are mainly located at synovial tissues under TMJ healthy and arthritis pathological conditions." (PMID 40502768, 2025).
asthma (1 paper, 2026). "Mechanistically, LYVE-1 promoted PDGF-BB-induced ASMC activation through PI3K/Akt signaling, highlighting LYVE-1 as a potential biomarker and potential therapeutic target for asthma." (PMID 41756236, 2026).
bacterial pneumonia (1 paper, 2022). Acute infection of the lung parenchyma caused by bacteria (e.g., Streptococcus pneumoniae, Haemophilus influenzae, Chlamydia pneumoniae, Mycoplasma pneumoniae, and Legionella pneumophila). "Nevertheless, CD44 and LYVE-1 jointly assist in immune cell migration within the lymphatic system to traffic cells to the lungs during bacterial pneumonia." (PMID 35634317, 2022).
bladder cancer (1 paper, 2007). "Our analysis indicates an increased lymphatic density during cancer progression and a co-localization of Ki-67 with some of LYVE-1-positive lymphatics, suggesting cancer-induced lymphangiogenesis, as it was recently suggested in human bladder cancer." (PMID 18047671, 2007). "Our present findings indicate that in addition to LYVE-1-positive lymphatic endothelial cells, during bladder cancer development, LYVE-1 positive macrophages were found in the bladder detrusor muscle isolated from SV40-lacZ mice." (PMID 18047671, 2007).
bladder tumor (1 paper, 2017). "Therefore, the significant expression of SLP-76, together with that of LYVE-1 and PDPN, observed in our cohort of patients led us to believe that its role in bladder tumor spreading might be preeminent and deserves further investigation." (PMID 28423532, 2017).
Cachexia (1 paper, 2020). Severe weight loss, wasting of muscle, loss of appetite, and general debility related to a chronic disease. "We found 71 proteins that correlated with cachexia severity via weight loss grade, weight loss, skeletal muscle index and radiodensity (r ≥ |0.50|, p ≤ 0.05), including some known cachexia mediators/markers (LEP, MSTN, ALB) as well as novel proteins (e.g., LYVE1, C7, F2)." (PMID 33334063, 2020).
Cerebral ischemia (1 paper, 2019). Restriction of arterial blood supply to the brain associated with insufficient oxygenation to support the metabolic requirements of the tissue. "In CLNs, expression levels of the lymphatic endothelium marker LYVE-1 were increased after cerebral ischemia, superficial CLNs showed slightly more robust responses compared to deep CLNs." (PMID 31757960, 2019).
chronic heart failure (1 paper, 2020). "In addition, human heart samples were obtained from healthy donors or patients with chronic heart failure, and the gene expression of lymphatic endothelial markers VEGFC, LYVE1, PDPN, and FLT4 was assessed." (PMID 33200983, 2020).
chronic lung allograft dysfunction (1 paper, 2019). Chronic lung allograft dysfunction encompasses a range of pathologies that cause a transplanted lung to not achieve or maintain normal function. "Chronic lung allograft dysfunction (CLAD)-free survival was also evaluated based on HA and LYVE-1 levels." (PMID 31227795, 2019).
colon carcinoma (1 paper, 2019). "The expression of LYVE-1 in colon cancer tissues and LYVE-1 and podoplanin antibody in frozen tumor tissues was observed." (PMID 31289961, 2019).
congenital diaphragmatic hernia (1 paper, 2024). A posterolateral defect of the diaphragm that allows passage of abdominal viscera into the thorax, leading to respiratory insufficiency and persistent pulmonary hypertension with high mortality. "LYVE1 was described as a marker in abnormal lymphatic system development studies, particularly in congenital diaphragmatic hernia, and increased nuchal translucency, as seen in Noonan syndrome cases." (PMID 39596121, 2024).
cutaneous squamous cell carcinoma (1 paper, 2019). "Since macrophages in cutaneous squamous cell carcinoma can also express LYVE-1." (PMID 31357710, 2019).
emphysema (1 paper, 2024). "Here we identify a role for lung collagen remodeling in preventing emphysema and loss of airway function in CS-induced COPD that is controlled by Lyve-1+ IMs." (PMID 39830508, 2024). "We investigated whether the reduction in CS-induced emphysema and small airway thickening observed in mice after depletion in Lyve-1+ macrophage was sufficient to improve lung function." (PMID 39830508, 2024). "Our data also support the potential protective role of collagen remodeling in COPD since the accumulation of more crosslinked collagen, especially type I, in lung prevents emphysema and bronchi thickness in CS-induced COPD mice depleted of Lyve-1+ macrophage." (PMID 39830508, 2024).
Encephalocele (1 paper, 2020). A neural tube defect characterized by sac-like protrusions of the brain and the membranes that cover it through openings in the skull. "The 13 weeks of gestation fetus with a vascular structure staining positive for LYVE1, Prox1, and CD31 was a termination of pregnancy because of the combination of omphalocele and encephalocele." (PMID 32516408, 2020).
endometriosis (1 paper, 2023). The growth of functional endometrial tissue in anatomic sites outside the uterine body. "Existing evidence indicate that the density of LYVE‐1 and Prox‐1 positive lymphatic vessels and the lymphatic vessel growth factor in endometriosis tissues of patients with endometriosis, especially intestinal DSIE, are significantly higher than those in normal human intestinal wall tissues." (PMID 37632165, 2023).
esophageal tumors (1 paper, 2021). "Intriguingly, LYVE-1 staining showed that the number of lymphatic vessels was robustly increased in esophageal tumors with low OTUD3 expression." (PMID 34853315, 2021).
gastric tumours (1 paper, 2009). "The LVD values in the gastric tumours were examined using LYVE-1 staining." (PMID 19738610, 2009).
hemangioma (1 paper, 2021). A benign vascular lesion characterized by the formation of capillary-sized or cavernous vascular channels. "As expected, we also found that lymphatic endothelial hyaluronan receptor-1 (LYVE1) and RTKs, such as EGFR, HER2, and HER3, were highly expressed in proliferating hemangiomas." (PMID 33400686, 2021).
hemophagocytic lymphohistiocytosis (1 paper, 2020). "The 4-month-old child with a vascular structure positive for LYVE-1, D2-40, CD31, and CD34 died of hemophagocytic lymphohistiocytosis, which was not present in the orbital tissues." (PMID 32516408, 2020).
hydrops fetalis (1 paper, 2017). Hydrops fetalis is a severe and challenging fetal condition usually defined as the excessive accumulation of fetal fluid within the fetal extravascular compartments and body cavities that manifests as edema, pleural and pericardial effusion and ascites. "Because impairment in lymphatic vascular formation causes hydrops fetalis with back skin edema, we examined the lymphatic vascular network formation in the back skin of Arf6−/− embryos by immunofluorescent staining for the specific marker of mouse LECs (mLECs) LYVE-1." (PMID 28900118, 2017).
infantile hemangiomas (1 paper, 2016). "LYVE-1 was detected as strongly expressed in proliferative infantile hemangiomas but not in pyogenic granulomas or intramuscular hemangioma lesions, suggesting an important role of these markers in the biology of infantile hemangioma." (PMID 26772808, 2016).
intestinal tumors (1 paper, 2008). "Six weeks after transplantation, intestinal tumors were harvested and evaluated for endothelial cells that co-expressed CD31 and Lyve-1." (PMID 19043576, 2008).
kidney inflammation (1 paper, 2022). "Along with increased renal expression of Il1b, TNF-α, Vcam1 and E-selectin, increased lymphatic vessel density and enhanced expression of Lyve-1 in the kidney further confirm that elevated level of circulating miR-505 leads to kidney inflammation in vivo." (PMID 35571179, 2022).
lymphangiosarcoma (1 paper, 2025). A malignant neoplasm arising from the endothelial cells of the lymphatic vessels. "Additionally, our findings reveal that SOX18 inhibition by Sm4 results in a decrease in lymphatic phenotype key markers (PROX1, VEGFR3, and LYVE1), indicating a potential role for SOX18 in promoting cancer‐related lymphangiogenesis as well as lymphangiosarcoma development and progression." (PMID 39791369, 2025).
lymphoma (1 paper, 2019). A malignant (clonal) proliferation of B- lymphocytes or T- lymphocytes which involves the lymph nodes, bone marrow and/or extranodal sites. "Cooperation between CD147 and the lymphatic vessel endothelial hyaluronan receptor-1 (LYVE-1) was also described in the regulation of chemoresistance in lymphoma through upregulation of the drug transporter/ABCG2 (BCRP, the breast cancer resistance protein)." (PMID 31744072, 2019).
metastatic melanoma (1 paper, 2023). A melanoma that has spread from its primary site to another anatomic site. "The LYVE-1 gene was also more highly expressed in metastatic melanoma." (PMID 37519819, 2023).
metastatic tumors (1 paper, 2021). "Our statistical analysis revealed that the expression level of SOAT1 was higher in LN-metastatic tumors and was positively correlated with the expression level of VEGFC, VEGFR3 and LYVE-1, which are lymphangiogenic growth factors." (PMID 34790132, 2021).
middle cerebral artery infarction (1 paper, 2019). Necrosis occurring in the middle cerebral artery distribution system which brings blood to the entire lateral aspects of each cerebral hemisphere. "LYVE1 levels have been reported significantly increased in patients with malignant middle cerebral artery infarction, and indicated as a potential marker of early prediction." (PMID 31262327, 2019).
muscular dystrophy (1 paper, 2011). Muscular dystrophy (MD) refers to a group of more than 30 genetic diseases characterized by progressive weakness and degeneration of the skeletal muscles that control movement. "Early pathology in mice with Lama2-deficient muscular dystrophy is marked by increased expression of TN-C in the extracellular matrix around muscle fibers, and decreased expression of LYVE-1 in lymphatic capillaries within the muscles." (PMID 21850221, 2011).
myositis (1 paper, 2023). "HRS-mediated induction of myositis results in a dramatic shift from M2-like macrophages expressing CD209f/C209g/CD163/Lyve1 marker genes (cluster 19) to macrophages expressing genes associated with alternative phenotypes (clusters 1, 2, and 6)." (PMID 37809058, 2023).
neuropathy (1 paper, 2024). A disorder affecting the nervous system that manifests with pain, tingling, numbness, and/or muscle weakness. "In DB mice, it is tempting to speculate that the age-related shift toward the anti-inflammatory, perivascular Lyve1+MHCIIlo phenotype and shift away from the nerve fiber-associated, Lyve1−MHCIIhi phenotype drive neuropathy in DB mice." (PMID 38502310, 2024).
pancreatitis (1 paper, 2025). Inflammation of the pancreas. "Limited information is available about LYVE1 in septic shock; however, our study identified plasma soluble LYVE1 levels at comparable levels in healthy volunteers, septic shock and pancreatitis." (PMID 40885913, 2025).
papillary thyroid carcinoma (1 paper, 2021). "In papillary thyroid carcinoma, LYVE1 was proved to be decreased and associated with poor prognosis." (PMID 34249481, 2021).
parasitemia (1 paper, 2023). "We found that blocking LYVE-1 resulted in an increased parasite burden in the lymphatic vasculature and decreased parasitemia." (PMID 37870927, 2023).
periodontitis (1 paper, 2025). An acute or chronic inflammatory process that affects the tissues that surround and support the teeth. "We found that periodontitis impaired mLV function and downregulated LYVE1 expression." (PMID 40552124, 2025). "LYVE1 expression levels were decreased significantly in the dura matter of periodontitis mice." (PMID 40552124, 2025). "In addition, the meningeal lymphatic drainage was impaired and the mRNA levels of lymphangiogenesis-related factor LYVE1 were decreased in the dura matter of periodontitis mice." (PMID 40552124, 2025).
peritonitis (1 paper, 2023). Inflammation of the peritoneum (tissue that lines the abdominal wall and covers most of the organs in the abdomen). "Specifically, we noticed that the inflammatory lipid mediator PGE2 adds to elevated Lyve1 expression in macrophages during the resolution phase in an in vivo peritonitis model." (PMID 37998039, 2023). "In line with the observed lower Lyve1 mRNA expression in the mPGES-1-inhibited peritonitis setting, fewer Lyve1-positive macrophages were present in the peritoneal cavity, when PGE2 synthesis was blocked and resolution was attenuated." (PMID 37998039, 2023). "Thus, in contrast to the CX3CL1/CX3CR1 axis, Lyve1 levels in macrophages negatively correlated with PGE2 levels in the course of peritonitis, indicating that Lyve1 might have a pro-resolving function." (PMID 37998039, 2023).
pterygium (1 paper, 2013). A wedge-shaped fibrovascular lesion arising from the bulbar conjunctiva and extending to the cornea. "Immunohistochemical staining for LYVE-1 and CD31 was performed on serial sections of human pterygium tissue." (PMID 23378730, 2013).
rheumatic fever (1 paper, 2015). A post-bacterial multisystem inflammatory disease occurring as a post-infectious, nonsuppurative sequela of untreated streptococcus pyogenes (Group A streptococcus [GAS]) pharyngitis, and mainly occurs in individuals aged 5 to 15 years. "We speculate that the interaction between M18 GAS and LYVE-1 augments association with lymphoid tissue and limits the spread to blood, thus providing a possible explanation for the infrequent association of M18 GAS with invasive disease and closer association with rheumatic fever." (PMID 26352587, 2015).
sarcoma (1 paper, 2025). A usually aggressive malignant neoplasm of the soft tissue or bone. "To investigate the synergy between KCL-HO-1i and chemotherapy in a second model, we utilized subcutaneous MN-MCA1 sarcoma tumors, which contain HO-1 expressing LYVE-1+CD206hi TAMs that reside in the Pv niche." (PMID 40768602, 2025).